EGFR (epidermal growth factor receptor)
Diseases named in the same sentence as EGFR in open-access papers (continued):
Sharing a sentence is not in itself a finding about the gene and the disease.
gastric cancer (continued). "Together, these previous studies further support an involvement of Cbl-b and its potential regulation of EGFR signaling in determining chemosensitivity of gastric cancer cells." (PMID 24351824, 2013). "The epidermal growth factor receptor (EGFR) signaling pathway regulates cell proliferation, differentiation, and survival, and is frequently dysregulated in esophageal and gastric cancers." (PMID 23874846, 2013). "In regards to esophageal and gastric cancer, higher EGFR and ERBB2 levels have been correlated with poor esophageal and gastric cancer survival." (PMID 23874846, 2013). "The aim of the present study was to investigate the cytotoxic activity of cytokine-induced killer (CIK) cells targeted by an epidermal growth factor receptor (EGFR)/CD3 bispecific antibody (BsAb) to the gastric cancer cell line SGC7901." (PMID 23833649, 2013). "Based on a genome-wide association study in a Han Chinese population, we examined 3443 SNPs in 127 genes in the EGFR pathway for 1942 esophageal squamous cell carcinomas (ESCCs), 1758 gastric cancers (GCs), and 2111 controls." (PMID 23874846, 2013). "The NUGC-3 stomach cancer cell line was used to detect EGFR phosphorylation because of its high EGFR expression." (PMID 23349913, 2013). "The present study confirmed that in the gastric cancer AGS cell line, EGF caused Tyr1173 phosphorylation of EGFR and the consequent activation of the key components of the PI3K/Akt-mediated pathway, including PI3K, Akt, mTOR and NF-κB." (PMID 24273605, 2013). "The overexpression of EGFR occurs in numerous human malignancies, including lung, breast, colon and gastric carcinomas." (PMID 23833649, 2013). "Regarding the curable stages, more data exist but the prognostic role of EGFR expression in operable gastric cancer remains controversial." (PMID 23153332, 2012). "While EGFR inhibitors for metastatic gastric cancer are currently under investigation, the prognostic role of EGFR in gastric cancer remains controversial." (PMID 23153332, 2012). "The epidermal growth factor receptor (EGFR) is a potential target of anticancer therapy in gastric cancer." (PMID 23153332, 2012). "In conclusion, EGFR inhibitors increased the sensitivity of SN38 in gastric cancer cells, especially in SN38-resistant gastric cancer cells." (PMID 21997136, 2011). "In gastric cancer, EGFR has become the target of choice, while EGFR inhibitors have proven only weakly effective." (PMID 21997136, 2011). "Expression of c-Met, phospho-Met, EGFR, and phospho-EGFR in ten CC cells and one gastric cancer cells were estimated by Western blotting." (PMID 21673683, 2011). "The goal of this study was to investigate ERBB2(HER2) and EGFR gene amplification and protein expression in gastric cancer." (PMID 21689422, 2011). "This is supported by our observation that the proliferation of parent gastric cancer cells was more highly decreased by the combination of an EGFR inhibitor and SN38 than by treatment with SN38 alone." (PMID 21997136, 2011). "Fluorescence in situ hybridization (FISH) and immunohistochemistry were used to analyze ERBB2 and EGFR gene amplification and protein expression in 69 cases of gastric cancer." (PMID 21689422, 2011). "EGFR gene amplification was present in 29.0% (20/69) of gastric cancers, including 34.1% (14/41) of patients with lymph node metastases and 10.7% (3/28) of patients without lymph node metastases, again representing a significant difference (P < 0.05)." (PMID 21689422, 2011). "We combined this data with results from histopathological and immunohistochemical analyses to determine the relationship between ERBB2 and EGFR expression status and clinicopathological variables in gastric cancer." (PMID 21689422, 2011). "Because cetuximab binds to the extracellular domain of EGFR, the obvious assumption was that the presence of EGFR on gastric cancer cell membranes would be predictive for response to cetuximab." (PMID 22152101, 2011).
gastric cancer (continued). "In vitro treatment of human gastric cancer cells (MKN-1 cells) with exogenous IL-8 enhances the expression of epidermal growth factor receptor (EGFR), matrix metalloproteinase (MMP)-9, VEGF-A, and IL-8 mRNAs." (PMID 20369064, 2010). "In gastrointestinal carcinomas, monoclonal antibodies targeting EGFR/EGFR-1 (cetuximab, panitumomab) and EGFR-2 (trastuzumab) have become part of the standard treatment armamentaria against colorectal and gastric cancers, respectively." (PMID 20961434, 2010). "Several articles have described some potential molecular targets for therapy in gastric cancer, such as epidermal growth factor receptor (EGFR), vascular endothelial growth factor (VEGF), recepteur d'origine nantais (RON)." (PMID 20929525, 2010). "We also confirmed that the EGFR itself was elevated in response to PAR1 activation in gastric carcinoma cells." (PMID 20723226, 2010). "An increase of EGFR protein expression in gastric cancer appears to be related to biological aggressiveness, although gene amplification has occurred only to a small extent." (PMID 19773760, 2009). "Gastric cancer patients with EGFR expression and low ligand levels had better outcomes with cetuximab/mFOLFOX6 treatment." (PMID 19127259, 2009). "There are limited but controversial reports regarding the prognostic implication of EGFR expression in gastric cancer." (PMID 19127259, 2009). "In conclusion, cetuximab in combination with mFOLFOX6 as a first-line treatment in gastric cancer showed the most promising results in patients with EGFR expression and low serum ligand levels (EGF and TGF-α)." (PMID 19127259, 2009). "EGFR inhibitors, small molecule tyrosine kinase inhibitors and monoclonal antibodies, have been explored in patients with esophageal and gastric cancers." (PMID 19636422, 2009). "In gastric cancer, EGFR is overexpressed in 18–91% of primary tumours and/or metastasis and correlated with a poor prognosis." (PMID 19773760, 2009). "In gastric cancer, EGFR is a promising target since it is frequently overexpressed, and clinical trials of cetuximab in the treatment of gastric cancer are ongoing." (PMID 19545448, 2009). "Recently EGFR inhibitors have been explored in patients with esophageal and gastric cancers, and the results are summarized by T. Dragovich and C. Campen in their review." (PMID 19750187, 2009). "This combination treatment in gastric cancer warrants further evaluation in a large-scale study with biomarker analysis, including EGFR and ligand status, for future optimisation of patient selection." (PMID 19127259, 2009). "The prognostic and predictive roles of epidermal growth factor receptor (EGFR) expression in gastric cancer remain controversial, and the reported frequencies of EGFR expression are varied in gastric cancer." (PMID 19259093, 2009). "This review article focuses on current experience in using therapeutic EGFR inhibitors as a therapy for patients with esophageal and gastric cancers." (PMID 19636422, 2009). "In contrast, overexpression of EGFR by IHC occurs less frequently in gastric cancer, at a rate of less than 40%." (PMID 19636422, 2009). "Epidermal growth factor receptor (EGFR) pathway has been implicated in pathophysiology of many epithelial malignancies, including esophageal and stomach cancers." (PMID 19636422, 2009). "In advanced gastric cancer patients treated mainly with 5-FU or cisplatin-based chemotherapy, lower expression of EGFR mRNA than the cutoff value was a strong predictor of poor survival by multivariate analysis." (PMID 19259093, 2009). "Some of the first clinical trials of EGFR inhibitors in esophageal and gastric cancers were those involving small molecule tyrosine kinase inhibitors." (PMID 19636422, 2009). "Some authors reported that EGFR is highly expressed in gastric cancer, suggesting its suitability as a target for receptor tyrosine kinase inhibitors." (PMID 18199332, 2008).
gastric cancer (continued). "We considered that searching for EGFR alterations in gastric cancer is likely to be clinically important in order to identify patients susceptible to respond to tyrosine kinase inhibitors." (PMID 18199332, 2008). "The presence of EGFR alterations in diffuse carcinomas is in contrast to what previously observed for other members of the ERBB receptor family in gastric cancer." (PMID 18199332, 2008). "In the present study, we did not identify a correlation between EGFR and HER2 protein expression and gene copy number in gastric carcinomas: only 7 cases showed co-expression of EGFR and HER2, and 3 cases were simultaneously FISH-positive for EGFR and HER2." (PMID 19061514, 2008). "Given its possible therapeutic relevance, we aimed to determine the frequency and type of structural alterations of the EGFR gene in a series of primary gastric carcinomas." (PMID 18199332, 2008). "Direct sequencing of the kinase domain of the EGFR gene was performed in a series of 77 primary gastric carcinomas." (PMID 18199332, 2008). "Conversely, Takehana and colleagues reported that overexpression of epidermal growth factor receptor is a rare event in gastric carcinoma and occurs predominantly due to EGFR gene amplification, confirming results from previous studies." (PMID 18199332, 2008). "When comparing gastric carcinoma harbouring EGFR alterations with carcinomas with normal EGFR status or copy number, we observed a significant association between EGFR structural alterations and increased tumour size." (PMID 18199332, 2008). "We demonstrate that EGFR structural alterations are rare in gastric carcinoma, but whenever present, it leads to tumour growth." (PMID 18199332, 2008). "PARs reportedly transactivates, i.e., phosphorylates, EGFR in a variety of cell systems such as gastric cancer cells and cardiac myocytes, and phosphorylated EGFR triggers EMT in human ovarian surface epithelium." (PMID 17433115, 2007). "In particular, the epidermal growth factor receptor (EGF-R) pathway appears to play a crucial role in gastric cancer progression." (PMID 12618892, 2003). "The epidermal growth factor receptor (EGF-R) pathway plays a pivotal role in the progression of human gastric cancer." (PMID 12618892, 2003). "Given that CIN represents approximately 70% of gastric cancer cases this analysis suggests that improved survival in a large proportion of gastric cancers could be achieved by adopting targeted therapy techniques against EGFR signaling." (PMID 41225774, 2025). "Interestingly, we uncovered that Ephrin A1 induced EMT of gastric cancer cells by activating EGFR signaling to promote metastatic capacities, which provides a new mechanistic insight for gastric cancer metastasis." (PMID 39838173, 2025). "Together, these results suggest that Ephrin A1 may induce EMT of gastric cancer cells through activating EGFR signaling." (PMID 39838173, 2025). "Here, we delineated the effects of HDACi on components of EGFR signalling in gastric cancer cells." (PMID 39864337, 2025). "However, EGFR targeting therapies in gastric cancer show only marginal effects, and the molecular mechanisms of oncogenic EGFR signaling remain poorly defined." (PMID 39838173, 2025). "To further explore the underlying mechanism of how Ephrin A1 induces EMT and metastasis of gastric cancer cells, we hypothesize whether Ephrin A1 interacts with other important tyrosine kinase receptors, such as EGFR, FGFR and integrins." (PMID 39838173, 2025). "The unwanted entinostat-mediated stimulation of the amphiregulin-EGFR axis in gastric cancer described for the first time in this study may thus be an important factor in an adaptive response of the tumor cells." (PMID 39864337, 2025). "The Ephrin A1/EGFR/EMT regulating axis may provide new strategies for targeting therapy in gastric cancer metastasis." (PMID 39838173, 2025).
gastric cancer (continued). "Future studies of the mechanical regulation of E-cadherin–EGFR complexes might also uncover mechanisms of disease progression and account for complex phenotypes observed in gastric cancers." (PMID 40908853, 2025). "Here, we report Ephrin A1 as a novel ligand of EGFR in gastric cancer." (PMID 39838173, 2025). "For gastric cancer, the predominant mechanisms that confer resistance to HER2-targeted therapy have been identified as the loss of HER2 amplification after treatment and the activation of alternative pathways, such as MET and EGFR." (PMID 41614808, 2025). "To determine whether EGFR signaling mediates the function of Ephrin A1 in regulating EMT of gastric cancer cells, we generated an EGFR knockout cell line by CRISPR-Cas9 system in MKN45 cells." (PMID 39838173, 2025). "Therefore, entinostat effects on the expression of EGFR and amphiregulin were studied in a panel of gastric cancer cell lines, tumor slice cultures and patient-derived xenografts." (PMID 39864337, 2025). "Moreover, gastric cancer patients with high Ephrin A1 expression levels or high EGFR phosphorylation levels had poor prognosis compared to low expression group." (PMID 39838173, 2025). "Since the landmark ToGA trial established trastuzumab, the anti-HER2 antibody, as first-line therapy for HER2-positive advanced gastric cancer, research has expanded to other targets including human epidermal growth factor receptor (EGFR), vascular endothelial growth factor (VEGF), and Claudin 18.2." (PMID 40830980, 2025). "Furthermore, a comprehensive multi-omic analysis of malignant gastric cancers revealed genomic amplifications of established cancer driver genes such as EGFR, ERBB2, MET, FGFR2, and CD44 in gastric cancer with peritoneal metastasis." (PMID 41009730, 2025). "The adaptive activation of the EGFR axis in gastric carcinoma cells after HDACi treatment shown in our study not only represents an important resistance factor to HDACi, but also opens up the possibility of combination therapy with EGFR inhibitors in the sense of acquired vulnerability." (PMID 39864337, 2025). "In the future, the combined application of anti-EGFR targeted therapies and STAT3 inhibitors could represent a promising investigational treatment strategy for patients with EGFR-positive gastric cancer." (PMID 39309860, 2024). "The downregulation of MED12 might explain why EGFR Inhibitor therapy was ineffective in previous clinical trials for advanced gastric cancer." (PMID 38467827, 2024). "We hypothesize that STAT3 may facilitate the development of EGFR-positive gastric cancer and contribute to drug resistance through interactions with molecules such as DARPP-32 and FGD5, possibly involving other yet-to-discovered mechanisms." (PMID 39309860, 2024). "Exploratory trials have already been conducted using EGFR-targeted therapies in gastric cancer." (PMID 39309860, 2024). "Developing such liposomal irinotecan formulations with EGFR or ABCG2 inhibitors could be a safer approach to achieving synergy with irinotecan in gastric cancer and other gastrointestinal cancers." (PMID 39033209, 2024). "It has been reported that GPS2 deletion activates AKT signaling to promote proliferation of triple-negative breast cancer cells (MDA-MB-231), and it inhibits the proliferation of gastric cancer cells by increasing the ubiquitylation of the epidermal growth factor receptor (EGFR)." (PMID 38755610, 2024). "Key metabolites such as linoleic acid, panaxynol, methyl linoleate, palmitoleic acid, and oleic acid have been identified to interact with critical targets in gastric cancer, including EGFR, MAPK1, MAPK3, and IL-6, significantly inhibiting the proliferation of gastric cancer cells." (PMID 39193331, 2024). "Additionally, gastric cancer cells overexpressing STAT3 often overexpress EGFR on the cell membrane." (PMID 39309860, 2024). "Furthermore, Tspan8 also plays a vital role in enhancing gastric cancer metastasis via activating the EGFR/Akt pathway." (PMID 38389703, 2024).
gastric cancer (continued). "In humans, EGFR is overexpressed in gastric cancer compared with normal gastric tissue." (PMID 39624840, 2024). "TAX prevents further progression of gastric cancer by inhibiting the EGFR/AKT1 signaling pathway." (PMID 39086391, 2024). "Interestingly, a MET-positive gastric carcinoma cell line became resistant to MET inhibitors through bypass activation of the EGFR pathway." (PMID 39769452, 2024). "Although the oncogenic role of EGFR is widely known, there is no agreement on the association between EGFR expression and the prognosis of gastric cancer." (PMID 37285389, 2023). "Furthermore, the IC50 of lapatinib, a HER-2 and EGFR tyrosine kinase inhibitor, is significantly negatively correlated with the CHPsigP score in breast (r=-0.457, P<0.001) and gastric cancer (r=-0.529, P=0.004)." (PMID 36761982, 2023). "Finally, gastric cancer-derived EV EGFR regulated the propensity of gastric cancer cells to colonize the liver by educating stromal cells in the microenvironment." (PMID 37350937, 2023). "Moreover, the level of EGFR amplification and overexpression predicted the response and survival benefit in a preclinical gastric cancer trial treating patient-derived xenografts with cetuximab." (PMID 37046849, 2023). "Moreover, even though the clinicopathological mechanism for the correlation between EGFR and gastric cancer is unclear, some studies have reported that it is related to older age, moderately to poorly differentiated histology, and a higher stage cancer." (PMID 37285389, 2023). "EGFR upregulation is a crucial process in gastric cancer cell metastasis." (PMID 38137380, 2023). "Although activation of EGFR signaling in gastric progenitor cells has been suggested as one of the major inducers of gastric cancers, our findings unexpectedly identified that EGFR signaling exerts a differentiation-promoting function, not a mitogenic function, in normal gastric homeostasis." (PMID 37386010, 2023). "ACh-induced cell proliferation was also inhibited under the effect of AG1478, an EGFR inhibitor, suggesting that ACh might act through M3 to activate EGFR signaling and promote cell proliferation in gastric cancer cells." (PMID 35565451, 2022). "MT inhibits gastric cancer cell proliferation in a dose-dependent manner by arresting cells in the G1 phase; it significantly inhibits gastric cancer cell migration and invasion by inhibiting EGFR phosphorylation." (PMID 36110092, 2022). "For example, exosomal integrins of the tumor can determine organotrophic metastases, and EVs secreted from gastric cancer also supply the epidermal growth factor receptor (EGFR), which may induce liver metastasis." (PMID 35886934, 2022). "Similarly, a study reported decreased expression of EGFR by lectin protein from Pseudomonas fluorescens in gastric cancer cells." (PMID 36547923, 2022). "In addition, the epidermal growth factor receptor (EGFR) is overexpressed in gastric cancer and positively related to poor clinical outcomes." (PMID 35889396, 2022). "The expression of EGFR tyrosine kinase is highly deregulated in gastric cancer tissues, as a result of H. pylori, indicating that EGFR tyrosine kinase inhibitor resistance could regulate the imbalance of gastric cancer." (PMID 36299773, 2022). "Now, Targeting EGFR is a therapeutic strategy in development in gastric cancer." (PMID 35991884, 2022).